TNF (tumor necrosis factor)
Diseases named in the same sentence as TNF in open-access papers (continued):
Sharing a sentence is not in itself a finding about the gene and the disease.
infection (continued). "In both lines, pathways associated with the host response to infection, including TNFα signaling via NF-κB, IL6/JAK/STAT3 signaling, and apoptosis, were significantly upregulated within 4 hours post-infection and remained elevated at 24 hours." (PMID 40766562, 2025). "This response involves the production of cytokines such as TNF-α, IL-1β, and IL-6, which recruit immune cells like neutrophils and macrophages to the site of infection." (PMID 39792889, 2025). "In response to bacterial stimulation, Nav1.8+ nociceptive neurons release CGRP, which subsequently acts on macrophages to inhibit tumor necrosis factor α (TNFα) production and ultimately the recruitment of neutrophils and monocytes to the site of infection." (PMID 40453085, 2025). "The inflammatory response triggered by the infection enhances TNF-mediated lipolysis, contributing to reductions in both adipocyte number and volume." (PMID 40864120, 2025). "The vB-SeS-01-liposome and free vB-SeS-01 both displayed similar modulating levels on TNF-α, reducing to one-third of the infection level." (PMID 39927265, 2025). "Our data confirm that exogenous AAT reduces α-defensin-inducing expression of TNFα in MDMs in the absence and presence of NTHi infection." (PMID 40013145, 2025). "For TNF-α, the difference was more significant at 3 h post-infection, while for IL-6 and CXC1/KC, the difference was more significant at 24 h post-infection." (PMID 40818988, 2025). "TNFα is a key pro-inflammatory cytokine involved in the regulation of acute immune responses during infection in mammals." (PMID 40723580, 2025). "At later times in the course of infection, the cellular population showed induction of an inflammatory response, related to TNF and IL-10, and a transition to adaptive immunity with evidence of upregulation of genes involved in MHC-II presentation." (PMID 41600804, 2025). "Previous studies have implicated Eiger/TNF in phagocytosis and host survival to pathogen infection, supporting the conservation of the TNF signaling pathway across insect taxa." (PMID 40608824, 2025). "In prophylactic settings, epithelioma cells pretreated with γ-PGA produced approximately twice the amount of TNF-α during infection, compared with HSV-1 infection alone." (PMID 41155933, 2025). "During infection, pro-inflammatory cytokines such as tumor necrosis factor alpha (TNF-α) activate RIPK1, which interacts with RIPK3 to phosphorylate MLKL, causing membrane rupture and necroptosis, thereby contributing to the overall PANoptotic response." (PMID 39861004, 2025). "We infected PKR knock-out, human or European rabbit PKR-expressing HeLa cells with MYXV∆029L∆156R and analyzed TNFα and IL-6 expression 12 h after infection using qRT-PCR." (PMID 40872887, 2025). "ACE2-Fc additionally reduces cytotoxicity following infection with different virus strains and inhibits the post-infection release of IL-6 and TNF-α from PBMCs." (PMID 40571942, 2025). "We observed that nine biomarkers (fractalkine, IFNγ, IL-5, IL-6, IL-10, IL-12, IL-13, IL-21, and TNFα) had significantly increased levels post-infection with subtype C HIV-1 compared to the pre-infection levels." (PMID 40862133, 2025). "LINC02528+/– macrophages exhibited significantly upregulated transcriptional and translational levels of IL-1β upon H37Rv infection, while exerting minimal impact on TNF-α and IL-6 expression." (PMID 41433368, 2025). "LF82 infection of confluent T84 cells significantly increased the release of IL-1β, IL-8, and TNF-α." (PMID 41163391, 2025). "S. suis-induced splenocytes depletion is alleviated in TNF-α-/- mice in the early stage of infection, which indicates that the inflammatory mediator TNF-α targets B cells and induces apoptosis through the TNF receptor in spleens." (PMID 40732121, 2025). "SSO pre-treatment reduced the production of inflammatory cytokines IL-6 and TNF-α on day 3 post-infection, with the lowest levels observed in the group that received intranasal SSO 6 h prior to infection." (PMID 40137298, 2025).
infection (continued). "The production of pro-inflammatory cytokines like TNF-α, increased by stimulating macrophages, which are the primary source of these cytokines throughout intrinsic infection phases." (PMID 39762829, 2025). "Complementary ELISA data demonstrated a significant augmentation in the secretion of cytokines IFN-γ, IL-4, IL-6, IL-17A, TGF-β, GATA-3, T-bet, IL-10, and TNF-α in the Pm_OMVs-infected group relative to the Pm group at 24 hours post-infection (P < 0.01)." (PMID 41306977, 2025). "We found that infection with all strains of Ot upregulated the expression of IL-6, TNF-alpha, IL-1ß, and CXCL-10 (human macrophages only) both in the presence and absence of IFN-γ." (PMID 40587585, 2025). "Both E. coli O142 and E. coli O142ΔestA infection altered gene expression levels of cancer-related cytokine-cytokine receptor interaction, TNF signaling pathway, and OXPHOS pathway." (PMID 40395804, 2025). "GSEA revealed that aging increased the signature of type I interferon response, TNF signaling, antigen presentation, arachidonic acid metabolism, and sphingolipid metabolism, which are involved in infection‐induced inflammation." (PMID 40396260, 2025). "TNF-α expression in all three tissues also showed a significant increase with infection duration (p < 0.05)." (PMID 40284708, 2025). "In our study, in women with PCOS and confirmed infection with any atypical pathogen (n = 196), we analyzed the levels of proinflammatory cytokines, such as IL-1β, IL-6 and TNF-α, which are important in this type of infection." (PMID 40647668, 2025). "We found that treatment with 5 mg/mL CNF significantly reduced the initial infection rate and significantly decreased the levels of cytokines (IL-β, TNF-α, and IL-6) in the host serum 12 and 24 h after infection (all P < 0.05)." (PMID 40270824, 2025). "Their production in the liver is stimulated through IL-1β, IL-6, and TNF-α, in response to infection, inflammation, or injury." (PMID 40943382, 2025). "TNFα was measured using ELISA in the cell supernatants 48 h after OV (MG1 or VSVΔ51) infection, SMAC mimetic treatment, or OV plus SMAC mimetic treatment." (PMID 41488671, 2025). "Herbs that possess anti-coccidial properties due to their tannin content can lower inflammatory cytokines like TNF-α in peripheral serum and boost the body’s defenses against infection (IL-10 and IgA)." (PMID 39762829, 2025). "Our results indicate that HAdV-C5 infection inhibits TNFα-mediated NF-κB activation by relocating IKKα to the nucleus (and, thereby, presumably disrupting IKK complex formation), where it supports viral replication." (PMID 40103806, 2025). "Although TNF production by myeloid cells is important for initial immune responses, it becomes redundant in the later stages of infection." (PMID 40825006, 2025). "This would explain the slight decrease in TNF-α expression as the infection progressed and the increase in IL-10 in infected animals." (PMID 40743218, 2025). "The increase in TNF-α in the model group highlights the severity of infection-related inflammation, and the reduction of TNF-α by RmmLII demonstrates its ability to alleviate damage." (PMID 40170927, 2025). "Our results also showed that E. coli XH197291 infection elevated IL-1β and TNF-α levels in the duodenum and ileum of Zi geese." (PMID 40963585, 2025). "TNF-α expression levels was significantly upregulated in all three infection groups at 12 hpi and 1 dpi." (PMID 40723822, 2025). "TNF‐α is a pluripotent and proinflammatory cytokine produced by activated macrophages during infection, thereby increasing leukocyte accumulation and amplifying the inflammatory cascade." (PMID 39612214, 2025). "IL-1, IL-6, and TNF-α are important pro-inflammatory cytokines released during the early stages of infection." (PMID 41150385, 2025).
infection (continued). "This phenotype was associated with reduced production of proinflammatory cytokines, including IL-6, TNF-α, and IL-1β, as well as diminished nitric oxide (NO) synthesis, all of which are critical for effective infection control." (PMID 41294882, 2025). "In this study, after the administration of AB-WE to goldfish and following pathogen infection, the expression of inflammation-related factors (IL-6, IL-8, TNF-α, and IL-1β) displayed a significant reduction (p < 0.05) in visceral tissues." (PMID 40805047, 2025). "Demographic data on reports of infections and infestations related to drug in treatment with TNF-α inhibitors in older adults in the FAERS database." (PMID 40371340, 2025). "Pro-inflammatory cytokines are released by infection, including TNF-α, IL-6, and IL-18, mediating inflammation and clinical symptoms." (PMID 40034419, 2025). "AM from resisters responded with a stronger TNF signature at 6 hours after infection while at 24 hours after infection, AM from LTBI displayed a stronger IFN-γ signature." (PMID 39836471, 2025). "They inhibit the activation of immune system receptors, such as TLR2, and the production of pro-inflammatory cytokines like TNF-α, favoring infection persistence." (PMID 40005812, 2025). "GXM negatively modulates microbicidal mechanisms during in vitro infection of murine macrophages with L. major, leading to higher parasite loads after 3 days post-infection, along with lower levels of NO (indicated by nitrite) and TNF-α." (PMID 41156732, 2025). "Challenge with M.tb leads to infection of macrophages, monocytes, and dendritic cells and a subsequent decrease in TNF-α, IFN-γ, and other proinflammatory cytokines." (PMID 40285479, 2025). "In contrast, in subtype A infected individuals, only two biomarkers (IL13 and TNFα) had significantly increased levels post-infection." (PMID 40862133, 2025). "Subsequently, the activated Th1 cells produces IFN-γ and TNF-α that recruit phagocytes to the site of infection and boost the cytotoxic activity of NK cells and CD8+ cytotoxic T lymphocytes." (PMID 39858163, 2025). "A2A-AR plays an important role in CDI because its deletion or inhibition in a mouse model of infection reduces survival as a consequence of increased toxicity and the inflammatory response characterised by increased TNF-α and IFN-γ." (PMID 40646589, 2025). "IHC staining revealed that intraperitoneal arginine administration suppressed infection-induced upregulation of proinflammatory cytokines IL-6 and TNF-α." (PMID 41181117, 2025). "In this study, after the cellular antioxidant system wasinactivated (6 to 8 h post-infection), the inflammatory cytokines mRNA IL-1β, IL-6, IL-8, and TNF-α further increased and reached the maximum value 8 h post-infection." (PMID 41343264, 2025). "APR is a systemic phenomenon that accompanies inflammation, in which IL-6, interleukin(IL)-1β (IL-1β), and tumour necrosis factor-α (TNF-α) synergistically cooperate to mitigate potential infection and further tissue injury." (PMID 40497942, 2025). "As expected, pro-inflammatory cytokines like IL-6, IL-1β, and TNFα were upregulated during infection, while TNFα was higher in SCFM2-Scnn1b-Tg infected mice than SCFM2-C57BL/6 infected mice." (PMID 40512037, 2025). "These pathways likely reflect a functional immune response signature characteristic of cells responding to infection, inflammation, or immune-modulating therapies such as Mesalazine, Cortisone, and TNFα-blockers." (PMID 40362323, 2025). "Before the infection, TNF-α and IL-1β expression significantly increased in groups fed oregano-supplemented diets compared to the control, whereas NF-κB expression levels remained unaffected." (PMID 41188425, 2025). "One day after infection, the hemogram is still normal, but circulating TNF-α, IL-1β, and CCL2 were markedly lower in infected hypothyroid mice with respect to euthyroid mice, while CXCL10 levels were higher." (PMID 41263555, 2025).
infection (continued). "Probiotics also have a negative effect on biofilm formation and modulate the host cell immune response to infection by influencing the balance of pro- and anti-inflammatory cytokines (e.g., IL-8, IL-10, TNFα, IL-1β, and IL-4)." (PMID 41009849, 2025). "As 20% of the participants reported resolution of symptoms 4–12 weeks after infection, the trends of IL–1β, IL–6, and TNF levels in these patients over time were also assessed." (PMID 40217938, 2025). "Pharmacological inhibition of DRP1 identified the role of ELMO1-DRP1 pathway in the regulation of pro-inflammatory cytokine TNF-α following infection." (PMID 41250600, 2025). "Nonetheless, elevated IL-1β and TNF-α levels have been reported in the later stages of infection with virulent PRRSV strains, and HP-PRRSV is known to induce systemic cytokine responses, including TNF-α, IFN-α, IL-1, and IL-6, around 7 dpi." (PMID 40630508, 2025). "After drainage, HMGB1, IL-1, IL-6, and TNF-α in the bile of AOSC patients were reduced as infection decreased." (PMID 40054422, 2025). "Second, the IL-13-induced secondary inflammatory cluster–enriched for IL-15, TNF-NFκB signaling, ER stress, and cell-death pathways–was most strongly induced at later infection timepoints." (PMID 41427379, 2025). "The IL-1β, IL-18, and TNF-α mRNA levels were decreased in the Pro10, Pro20, Pro40, Amo20, Pro20 + Amo20, and Bai100 groups compared with the infection group (p < 0.001)." (PMID 40305201, 2025). "It has been reported that ORF7b functions in suppressing IFN-interferon production during early infection to facilitate evasion of host detection and induction of cell apoptosis by promoting the expression of TNF-α and IL-6." (PMID 40668819, 2025). "KEGG analysis shows the enrichment of DE‐PRGs in pathways related to NF‐kappa B signaling, apoptosis, infection, and TNF signaling." (PMID 39854144, 2025). "In contrast, HMPV-induced TNF mRNA expression in MDMs was significantly reduced at 3 h post-infection following silencing of either SLAMF1 or TLR4." (PMID 41346628, 2025). "LPS interacts with Toll-like receptor 4 (TLR 4) to activate the macrophages involved in the infection response, leading to the production of various molecules and pro-inflammatory cytokines, such as interleukin (IL)-6 and tumor necrosis factor alpha (TNF-α)." (PMID 40722600, 2025). "Following infection of the central nervous system (CNS), microglia and astrocytes become hyperactivated, releasing excessive proinflammatory cytokines such as tumor necrosis factor-alpha (TNF-α) and interferon-gamma (IFN-γ)." (PMID 40760662, 2025). "Emerging markers such as G-CSF, TNF, presepsin, PSP, MR-proADM, sIL-2R, sTNFR2, Flt3L, and IP-10 are beginning to define more nuanced immune profiles associated with infection type and severity." (PMID 40647525, 2025). "The selective effect of TLR4 knockout on HMPV-mediated TNF was further reflected at the protein level: secreted TNF was significantly reduced at 20 h post-infection in TLR4 KO cells, while secretion of the IFN-inducible chemokine CXCL10 remained unchanged." (PMID 41346628, 2025). "In the baseline infection group (n = 6), the TNF-α concentration was 28.9 ± 12.4 pg/cornea and IL-8 concentration was 196.6 ± 80.5 pg/cornea; these enhanced levels confirmed the presence of an inflammatory response to the induction of bacterial keratitis." (PMID 41384791, 2025). "Tumor necrosis factor alpha (TNFα) is a central pro-inflammatory cytokine that mediates host immune responses during infection." (PMID 40723580, 2025). "Key findings include significant associations between polymorphisms in TLR4 (rs4986790), IL-10 (rs1800896), TNF-α (rs1800629), and MBL2 (rs1800450) with infection susceptibility, disease severity, and survival outcomes." (PMID 40692949, 2025).
infection (continued). "Following infection, macrophages not only directly eliminate fungi by phagocytosis but secrete a series of pro-inflammatory cytokines (e.g., IL-1β, TNF-α, IL-6, and IL-12), biotic factors (e.g., ROS and NO), and enzymes (e.g., lysozyme and acid phosphatase)." (PMID 39949625, 2025). "Data from termination 4 days post-infection indicated a 3-fold significant decrease of TNF-α in the 100 μg/mL FDSP treatment." (PMID 41155292, 2025). "Granuloma stability is maintained by pro-inflammatory cytokines and chemokines, particularly TNF-α, which promotes leukocyte migration to the infection site." (PMID 40429667, 2025). "After C50041ΔtrmE infection, there was a significant increase in the mRNA of TNF-α (p < 0.01) on day 1 and IL-1β (p < 0.001) on day 7, but the mRNA of IL-1β (p < 0.05) and IFN-γ (p < 0.05) was significantly reduced on day 4 compared to that of SE (C50041)." (PMID 40731965, 2025). "OTUD7B (Cezanne) prevents tumor necrosis factor (TNF)-induced apoptosis of dendric cells in infection and facilitates T cell activation and inflammatory responses by regulating Zap70 ubiquitination." (PMID 39985644, 2025). "TNF-α increased throughout acute infection and was significantly elevated in infected mice by 9 dpi." (PMID 39780244, 2025). "When we compared the expression of inflammatory cytokine response of adult and pediatric cells upon HMPV and RSV infection, we observed that adult cells produced more pro-inflammatory cytokines (IL-1β, IL-6, IL-8, and TNF-α) following infection." (PMID 40143308, 2025). "In the spleen, the increase in CFU increased with levels of IL-6 (0.82) and TNF-α (0.83), which shows that the increase in CFU in the spleen is associated with the immune profile previously observed during infection by this fungus." (PMID 41156648, 2025). "Macrophages derived from STS mice produced higher levels of several soluble factors, including CCL5/RANTES, G-CSF, TNF alpha, and IL-6, than macrophages from CcS-11 mice even before infection." (PMID 39875898, 2025). "In assessing the innate and adaptive immune responses during infection, significant reductions in TNFα and select chemokines that aid recruitment of neutrophils and T-cells were observed in Tac1−/− mice compared to WT." (PMID 40501768, 2025). "We found that 2.5 mg/kg M3 treatment greatly reduced proinflammatory cytokine (IL6, IFNγ, TNFα, and IL-1β) mRNA expression in the lung 3 days after infection, which explains the high efficacy of M3 in protecting mice from lethal IAV infection." (PMID 39601535, 2025). "In Mycobacterium bovis bacillus Calmette-Guerin (BCG) infection, macrophages also upregulate glycolysis in parallel with TNF and IL-1β secretion." (PMID 40427602, 2025). "The pathway-enriched analysis identified FoxO signaling, mitogen-activated protein kinase (MAPK) signaling, apoptosis, infection, Toll-like receptor signaling, and TNF signaling pathways." (PMID 40455583, 2025). "PM10 pre-exposure suppressed apoptosis and reduced the expression of pro-inflammatory cytokines including IFN-γ, IP-10, and TNF-α during Delta infection." (PMID 41561095, 2025). "In the acute phase of infection, parasite antigens elicit a robust Th1 response marked by elevated levels of proinflammatory cytokines, including TNF-α, IL-1, and IL-6." (PMID 40365538, 2025). "Regulation of the monocyte activation and deactivation by control of apoptosis has been shown to be important in response to TNF-alpha (TNFα) mediated infection." (PMID 40097954, 2025). "The IL-1β, IL-18, and TNF-α protein levels were reduced in the Pro10, Pro20, Pro40, Amo20, Pro20 + Amo20, and Bai100 groups compared with the infection group (p < 0.05) (except TNF-α in the Pro10 group)." (PMID 40305201, 2025). "Conversely, individual strains elicited significant upregulation of TNF-α expression in infected PAM-KNU cells, although VR-2332 infection upregulated TNF-α expression more remarkably." (PMID 40302751, 2025).